TMT1A (thiol methyltransferase 1A)
Description:
Thiol S-methyltransferase that catalyzes the transfer of a methyl group from S-adenosyl-L-methionine to alkyl and phenolic thiol-containing acceptor substrates. Together with TMT1B accounts for most of S-thiol methylation activity in the endoplasmic reticulum of hepatocytes. Able to methylate the N6 position of adenosine residues in long non-coding RNAs (lncRNAs). May facilitate lncRNAs transfer into exosomes at the tumor-stroma interface. Promotes osteogenic and odontogenic differentiation by regulating the expression of genes involved in stem cell differentiation and survival. Targeted from the endoplasmic reticulum to lipid droplets, where it recruits cellular proteins to form functional organelles. (Microbial infection) May be involved in the assembly and release stages of hepatitis C virus (HCV) life cycle and thus play a crucial role in HCV propagation.
Synonyms: METTL7A; DKFZP586A0522; AAM-B; AAMB
Tractability: Antibody: its Gene Ontology location is reachable by antibodies, with high confidence; UniProt predicts a signal peptide or a membrane-spanning region. PROTAC: ubiquitination databases record sites on it.
Target class: Enzyme; Transferase
Gene: Protein-coding gene on chromosome 12 (50,923,472 to 50,932,510, forward strand). Ensembl gene ENSG00000185432.
Subcellular location: Lipid droplet; Endoplasmic reticulum; Membrane; Microsome; Cytoplasm, cytosol
Subcellular location (Human Protein Atlas): Lipid droplets
Pathways (Reactome):
Immune System: Neutrophil degranulation
Gene Ontology:
Molecular function: mRNA m(6)A methyltransferase activity; protein binding; RNA methyltransferase activity; thiol S-methyltransferase activity; methyltransferase activity; S-adenosylmethionine-dependent methyltransferase activity
Biological process: lncRNA processing; odontogenesis; osteoblast differentiation
Cellular component: endoplasmic reticulum; lipid droplet; membrane; extracellular region; tertiary granule lumen; cytosol
Genetic constraint (gnomAD): Loss-of-function variants: 10 observed, 14.57 expected, observed/expected ratio (o/e) 0.69, 90% interval 0.42 to 1.16. The upper end of that interval is the gene's LOEUF score, 1.16, which puts it in group 5 of 6, group 1 being the genes least tolerant of losing a copy. Missense variants: 276 observed, 310.83 expected, observed/expected ratio (o/e) 0.89, 90% interval 0.8 to 0.98. Synonymous variants: 106 observed, 124.73 expected, observed/expected ratio (o/e) 0.85, 90% interval 0.73 to 1.
Homologues: Orthologues: chimpanzee TMT1A (99% identical), macaque TMT1A (88% identical), rabbit TMT1A (86% identical), mouse Tmt1a (85% identical), mouse Tmt1a2 (81% identical), guinea pig TMT1A (80% identical), dog TMT1A (80% identical), mouse Tmt1a3 (80% identical), rat Tmt1a (63% identical), zebrafish tmt1a.2 (52% identical), zebrafish tmt1a.3 (52% identical), zebrafish tmt1a.1 (51% identical), and 4 more. Paralogues in human: TMT1B (57% identical), AS3MT (17% identical), METTL27 (16% identical), COQ5 (13% identical).
Diseases named in the same sentence as TMT1A in open-access papers:
TMT1A is named in the same sentence as 43 diseases in open-access papers, as found by Europe PMC text mining. Sharing a sentence is not in itself a finding about the gene and the disease. The quoted sentences say what the papers report.
thyroid cancer (7 papers, 2017 to 2026). "In the context of thyroid cancer, a downregulation of TMT1A mRNA expression has been observed, which correlates with gene body methylation at the +4919 CpG site." (PMID 41541671, 2026).
lung adenocarcinoma (6 papers, 2022 to 2026). A carcinoma that arises from the lung and is characterized by the presence of malignant glandular epithelial cells. "The role of thiol methyltransferase 1A (TMT1A) in lung adenocarcinoma (LUAD) progression and the immune microenvironment remains unclear." (PMID 41541671, 2026).
tumor (20 papers, 2017 to 2026). "Collectively, these transcriptomic findings substantiate the tumor-suppressive role of TMT1A through the restraint of oncogenic signaling and the maintenance of immune homeostasis." (PMID 41541671, 2026). "Conversely, TMT1A overexpression in A549 cells markedly inhibited their tumor sphere formation ability." (PMID 41541671, 2026). "Consistent with the findings of subcutaneous transplanted tumor model, TMT1A overexpression significantly reduced the number of metastatic lung nodules compared with the vector group, further supporting its inhibitory role in LUAD progression." (PMID 41541671, 2026). "Currently, TMT1A is predominantly regarded as a tumor suppressor in oncological research." (PMID 41541671, 2026). "TMT1A expression inhibits colony formation, migration, and ECM invasion, suggesting that TMT1A may act as a tumor-suppressor gene." (PMID 41541671, 2026). "Overexpression of TMT1A significantly reduced both tumor volume and weight." (PMID 41541671, 2026). "Although these findings suggest that TMT1A may function as both a tumor suppressor and an immune regulatory factor, most studies to date remain limited to bioinformatic analyses." (PMID 41541671, 2026). "In addition, TMT1A plays a regulatory role in stem cell differentiation processes such as osteogenic and odontogenic differentiation, suggesting that it may influence the self-renewal and multi-directional differentiation capabilities of tumor stem cells." (PMID 41541671, 2026).
cancer (18 papers, 2017 to 2026). A tumor composed of atypical neoplastic, often pleomorphic cells that invade other tissues. "Alterations in TMT1A expression have been linked to several cancers, including liver, thyroid, breast cancers, choriocarcinoma, and LUAD." (PMID 41541671, 2026). "To elucidate the biological function of TMT1A, we conducted cancer cell proliferation and migration assays." (PMID 41541671, 2026). "Currently, research into the role of TMT1A in cancer immunity is relatively scarce." (PMID 41541671, 2026). "In our investigation, the TMT1A methylation level in cancer tissues was higher than that in normal tissues and negatively correlated with TMT1A mRNA expression." (PMID 41541671, 2026). "Using machine learning algorithms, including RF, SVM, GBM (XGBoost), and DT, the genes CDH3, DKC1, ESM1, MUSTN1, RCC2, TMT1A, and VEGFD were selected as key features from the tissue dataset to best discriminate between cancer and control samples and were used to design the predictive model." (PMID 40425785, 2025).
TMT1A also shares sentences with these, for which no sentence is quoted: choriocarcinoma (4 papers); breast carcinoma (3); bladder urothelial carcinoma (2); colon cancer (2); hepatocellular carcinoma (2); lung carcinoma (2); mesothelioma (2); multiple myeloma (2); osteosarcoma (2); renal carcinoma (2); sarcoma (2); schizophrenia (2); adrenal cancer (1); cervical squamous cell carcinoma (1); Cognitive impairment (1); colorectal cancer (1); COVID-19 (1); cutaneous melanoma (1); diabetic nephropathy (1); endocervical adenocarcinoma (1); esophageal carcinoma (1); glioblastoma multiforme (1); glioma (1); head and neck squamous cell carcinoma (1); kidney clear cell carcinoma (1); liposarcoma (1); lung squamous cell carcinoma (1); melanoma (1); mitochondrial disease (1); non-small cell lung carcinoma (1).
A further 9 diseases each share a sentence with TMT1A in 1 paper.